RPSA (ribosomal protein SA)
Diseases named in the same sentence as RPSA in open-access papers (continued):
Sharing a sentence is not in itself a finding about the gene and the disease.
cancer (25 papers, 2003 to 2025). A tumor composed of atypical neoplastic, often pleomorphic cells that invade other tissues. "The effect on autophagy modulation of PrPC linked to its receptor RPSA in cancer is even less investigated." (PMID 37452879, 2023). "According to these criteria, five genes (RPL5, RPL11, RPS5 (uS7), RPS20 (uS10), RPSA (uS2)) were significantly mutated in four different cancer types." (PMID 28147343, 2017). "The study of the mechanisms underlying the PrPC/RPSA interaction might help not only in understanding the pathogenesis of different cancers but also for developing prophylactic and therapeutic measures, as well as for diagnosis." (PMID 37452879, 2023). "β-galactosidase was found to be strongly expressed in Caco-2/15, SW480, and T84 compared to SW620 and HT29 cells while RPSA had a relatively comparable level of expression in all cancer cell lines." (PMID 38606907, 2024). "EDPs released in the extracellular microenvironment during tumoral remodeling of the stroma stimulate cancer cell migration by interacting with their membrane receptor, ribosomal protein SA (RPSA)." (PMID 38327525, 2024). "In the context of cancer, our finding is promising if we consider the possibility to modulate RPSA and Aβ levels." (PMID 37452879, 2023). "Regarding proliferation-promoting processes, the main mechanism first explored in cancer cells expressing high levels of RPSA was apoptosis." (PMID 37452879, 2023). "Beyond their physiological roles, recent findings revealed the involvement of both PrPC and RPSA in pathological condition, such as cancer." (PMID 37452879, 2023). "In common with PrPC, several investigations have clearly demonstrated an increase of RPSA expression in epithelium-derived cancers, as compared to the corresponding normal tissue." (PMID 37452879, 2023). "RPSA interaction with LM, the main extracellular matrix glycoprotein, makes the receptor a promoter of invasive and metastatic characteristics of cancer cells." (PMID 37452879, 2023). "EDPs stimulate cancer cell migration by interacting with their membrane receptor, ribosomal protein SA (RPSA)." (PMID 32733880, 2020). "EGCG was reported to exert its anti-cancer activity through the 10 amino acid sequence of RPSA, IPCNNKGAHS." (PMID 33396696, 2020). "We recently showed that EDPs induced cancer cell blebbing and shedding of extracellular vesicles through binding to RPSA." (PMID 32733880, 2020). "Thus, here we will exclusively report and discuss data on the involvement of PrPC and RPSA in autophagic mechanism, mainly in cancer." (PMID 37452879, 2023). "In a pathological context, the over-expression of PrPC and RPSA frequently reported in several cancer types, can be the consequence of the genomic instability and it likely represents a mechanism through which the cells enhance the DDR to counteract the accumulation of DNA damage." (PMID 37452879, 2023). "Whether RPSA is potent for disturbing NF-κB transcriptional activity in cancers still needs to be investigated." (PMID 38114488, 2023). "Specific antibodies for RPSA and siRNAs targeting RPSA are two therapeutic strategies employed in many tumorigenic in vitro cell lines and both effective in inhibiting the characteristics of multiple cancer hallmarks." (PMID 37452879, 2023). "In conclusion, despite evidence related to PrPC and RPSA interaction in cancer are beginning to be unveiled, future investigations may allow the development of therapeutic strategies to target this complex specifically." (PMID 37452879, 2023). "The primary aim of this review is to focus on the role of PrPC/RPSA interaction in the control of cancer hallmarks, such as proliferation, migration and invasion, genome instability and mutation, as well as resistance to cell death modulated by autophagic pathway." (PMID 37452879, 2023). "Herein, according to results of the dual-luciferase assay, we speculate that miR-587 may be involved in HCC progression by targeting RPSA—a well-established gene in cancers." (PMID 32964027, 2020).
cancer (continued). "Elastin was reported to interact with invasive cancer cells through RPSA." (PMID 33396696, 2020). "Besides being a constituent of the ribosome, RPSA also functions on the extracellular membrane as a laminin receptor and transduces extracellular signals regulating cancer-related pathways such as apoptosis and cell migration." (PMID 28147343, 2017). "Notably, the inhibition of APN has been reported to enhance ERK1/2 signaling in various cancer models, suggesting that RPSA may regulate the ERK1/2 pathway independently of APN." (PMID 40736249, 2025). "Moreover, the anti-cancer effect of epigallocatechin gallate (EGCG) molecules has been shown by its action on the inhibition of ribosomal protein SA (RPSA)/67LR, suggesting that the receptor could be an interesting target for reducing tumor growth." (PMID 38606907, 2024). "However, it is still unknown whether PrPC mutants can have an impaired trafficking in cancer cells and whether they are able, as compared to wild-type PrPC, to establish interaction with RPSA." (PMID 37452879, 2023). "Thus, targeting of TRPM7/RPSA complexes could be a promising strategy to reduce cancer cell migration in the neoplastic pancreas." (PMID 32733880, 2020). "Both the laminin-binding protein RPSA and the metalloproteinase ST3 responsible for its cleavage are known to be overexpressed in different cancers." (PMID 28147343, 2017). "We screened mutation and copy number data of respectively 4926 and 7322 samples from 16 cancer types and identified six altered genes (RPL5, RPL11, RPL23A, RPS5, RPS20 and RPSA)." (PMID 28147343, 2017). "As both RPSA and TRPM7 are overexpressed and regulate cancer cell migration, it is tempting to speculate that these two biomarkers could interact in PDAC." (PMID 32733880, 2020). "RPSA antibodies block EGCG anti-cancer activity but do not trigger the same effects, indicating that the polyphenol may act agonistically or allosterically." (PMID 33396696, 2020). "RPSA could also form a complex with the transient receptor potential melastatin-related 7 (TRPM7) that regulates pancreatic ductal cancer cell migration suggesting that RPSA could work through different pathways and be a promising target in the treatment of this cancer." (PMID 34873618, 2021).
tumor (25 papers, 2003 to 2025). "RPSA has also been implicated in the metastasis and invasion in hematological malignancies, as well as apoptosis and cellular proliferation in tumor cells." (PMID 32964027, 2020). "Under abnormal circumstances, RPSA may cause tumor metastasis, neurodegenerative diseases, and abnormal development." (PMID 33603733, 2020). "RPSA is a ribosomal protein with several pathophysiological functions in protein translation, cell adhesion, tumor cell invasion, viral cell entry, and small molecule sensing." (PMID 35546602, 2022). "The pro-tumor biological effects of AG-9 was previously reported to involve a lactose-insensitive receptor, the ribosomal protein SA (RPSA)." (PMID 33396696, 2020). "It is also suggested that RPSA is involved in regulation of the mitogen-activated protein kinase (MAPK) signaling pathway correlating with tumor dissemination." (PMID 31694957, 2020). "In summary, miR-587 overexpression inhibits tumor cell proliferation, migration, and invasion by directly downregulating RPSA mRNA in HCC." (PMID 32964027, 2020). "RPSA prevents cell apoptotic escape, allowing tumor progression." (PMID 33396696, 2020). "RPSA is involved in regulation of MAPK signaling pathway correlating with tumor dissemination." (PMID 31694957, 2020). "RPSA also prevents cell apoptotic escape, allowing tumor progression." (PMID 33396696, 2020). "In this context, RPSA is a laminin-binding protein with implications in tumour invasion." (PMID 30382192, 2018). "In our study, RPSA induced the phosphorylation of ERK1/2 in a dose-dependent manner, consistent with positive regulation in tumor cell lines." (PMID 40736249, 2025). "We also speculate that since the cells are mostly apoptotic after a 72‐h transfection with RPSA siRNA, the immune and proteasomal degradation systems are being activated to clear the apoptotic cells and any resulting debris to regulate the cell death process and avoid tumour‐promoting inflammation." (PMID 36579897, 2023). "RPSA induces the dephosphorylation of kinases ERK, JNK, and p38 and decreases the activity of the three MAPK cascades in tumor cell lines." (PMID 31694957, 2020). "We found that RPSA was not modulated in tumor tissues relative to the resection margins." (PMID 40141206, 2025).
infection (12 papers, 2019 to 2025). The state of being infected such as from the introduction of a foreign agent such as serum, vaccine, antigenic substance or organism. "Consistent, the in situ association of RPSA with EdU-labeled HSV-1 genome DNA was observed during infection in DNA pull-down assay." (PMID 38114488, 2023). "Overall, these results suggest that RPSA is an essential host factor that limits the infection of porcine enteric coronaviruses by either inhibiting the ERK1/2 signaling pathway or reducing APN expression." (PMID 40736249, 2025). "Indirect immunofluorescence analysis further revealed significantly reduced levels of PEDV N protein in RPSA-KO cells after infection at MOIs of 0.01 and 0.1 at 12 hpi." (PMID 40736249, 2025). "After SS2 infection, co-localization of RPSA and VIM dramatically increased, particularly where bulges were observed; these were in contrast to uninfected cells (red arrow)." (PMID 38331785, 2024). "RPSA, also known as the 37/67-kDa laminin receptor, has been found to be related to a variety of diseases, including infections, tumors and neurodegenerative diseases." (PMID 38114488, 2023). "In macrophages, RPSA expression levels were altered after infection with Mycoplasma pleuropneumoniae and porcine circovirus type 2 or after BCG vaccination." (PMID 37007947, 2023). "Mechanistically, nucleus-localized RPSA is phosphorylated at Tyr204 upon infection, then recruits ISWI complex catalytic subunit SMARCA5 to increase chromatin accessibility of NF-κB to target gene promotors without affecting innate signaling." (PMID 38114488, 2023). "There is great interest in RPSA-triggered epigenetic remolding in establishing trained immunity that protects the host against secondary infection." (PMID 38114488, 2023). "Herein, we provide the necessary foundation for understanding the role of RPSA+ PMNs in SS2 infections." (PMID 33603733, 2020). "We found that the phagocytic and bactericidal capacities of RPSA+ PMNs were upregulated during SS2 infections." (PMID 33603733, 2020). "RPSA expression on the surface of PMNs was determined via flow cytometry following infection with SS2 (MOI=2)." (PMID 33603733, 2020). "A gradual increase in RPSA protein abundance was observed as infection progressed at the early infection period (from 2 to 8 h postinfection [hpi]), and the abundance remained almost unchanged after 8 hpi (from 8 to 16 hpi)." (PMID 31694957, 2020). "RPSA distributed on the surface of cellular membranes also mediates infections by pathogens, such as S. pneumoniae, N. meningitis, H. influenzae, E. coli K1, and S. suis." (PMID 33603733, 2020). "To explore the role of RPSA in the PEDV infection cycle, we first examined whether RPSA affects virus attachment or entry." (PMID 40736249, 2025). "In addition, expression of the protein-coding genes CXCL10, IFIT1, NCOA7, IFIT2, SIX3, and RPSA was increased during infection." (PMID 40510596, 2025). "Furthermore, increasing intracellular calcium ions (Ca2+) in response to SS2 infection further facilitates the liquid-like condensation of RPSA and aggravates ENO-induced HBMEC cell apoptosis." (PMID 38331785, 2024). "Partly, RPSA+ PMN may be extremely useful to control the infection as a therapeutic cellular population, following novel insights into the special PMN population." (PMID 33603733, 2020). "However, the incubation of susceptible cells using the anti-RPSA antibodies did not block the infection of FMDV." (PMID 31694957, 2020). "Viral titration revealed significantly lower viral loads in RPSA-KO cells compared to WT cells at an MOI of 0.01, measured at 6, 12, and 18 h post-infection (hpi)." (PMID 40736249, 2025). "During infection by viruses like HSV-1 or IAV, nuclear phosphorylated RPSA recruits SMARCA5, a process that enhances chromatin accessibility at NF-κB target gene promoters and facilitates the transcription of pro-inflammatory cytokines." (PMID 41472165, 2025).
infection (continued). "For verification of the relationship between RPSA and Vimentin (VIM), the protein expression level of VIM after SS2 infection or ENO stimulation was analyzed." (PMID 38331785, 2024). "The survival rates of SS2-infected mice with knockdown of RPSA (50%) and HSPD1 (40%) were significantly increased at 36 h post-infection (shControl group, 0%)." (PMID 33618766, 2021). "This showed that the deletion of RPSA did not affect the attachment or adsorption ability of the virus particles, which is consistent with the previous conclusion that RPSA does not play a receptor role in PEDV infection." (PMID 40736249, 2025). "Co-immunoprecipitation assays using an RPSA-specific antibody and the nuclear lysate from viral-infected mouse bone marrow-derived macrophages (BMDMs) showed that RPSA was capable of interacting with both HSV-1 DNA and IAV genome RNA in infection." (PMID 38114488, 2023). "These indicated that RPSA+ PMN is going to be extremely useful to control the infection as a therapeutic cellular population without excessive inflammation." (PMID 33603733, 2020). "We found that after non-permeable membrane treatment, PMN in SS2 infection group significantly enhanced the membrane localization of RPSA." (PMID 33603733, 2020). "Interestingly, RPSA KO also significantly downregulated the expression of aminopeptidase N (APN) and inhibited infection by transmissible gastroenteritis virus (TGEV) and porcine deltacoronavirus (PDCoV), both of which belong to the swine enteric coronavirus group." (PMID 40736249, 2025). "However, the distribution and the role of RPSA in PMNs, as well as its correlation with infections have not yet been reported." (PMID 33603733, 2020). "The RPSA+ PMN cell count in the brain tissue of infected mice did not change 1 and 2 days post-infection, but at 3 days post-infection, their RPSA+ PMN cell count increased significantly compared to the past 2 days and was significantly higher compared to the control group." (PMID 33603733, 2020). "However, in the present study, we found that incubation of the cells using the anti-RPSA antibodies did not block the infection of FMDV." (PMID 31694957, 2020). "Further analysis of gidB and rpsA sequence data showed that all isolates in five clusters (Cluster III, VIII, XI, XV and XVI) were genotypically identical strains, highly suggestive of cross-transmission of infection among these patients or infection from a common source." (PMID 31806020, 2019). "Further analysis of gidB and rpsA carried out for selected cluster isolates showed that all isolates in five clusters (Cluster III, VIII, XI, XV and XVI) were genotypically identical strains, highly suggestive of cross-transmission of infection among these patients or infection from a common source." (PMID 31806020, 2019). "Overexpression of porcine RPSA in the insusceptible cells could not trigger FMDV infection, suggesting that RPSA was not responsible for FMDV entry and infection." (PMID 31694957, 2020).
neurodegenerative disease (4 papers, 2020 to 2022). A disorder of the central nervous system characterized by gradual and progressive loss of neural tissue and neurologic function. "RPSA has been implicated in neurodegenerative diseases and developmental aberrations." (PMID 33446247, 2021). "Studies have shown that knockdown of RPSA can lead to neurodegenerative diseases through apoptosis, which is consistent with our findings that the expression of RPSA in AD patients was downregulated through DNA methylation." (PMID 35615586, 2022). "Likely, agents that induce RPSA endocytosis could have therapeutic potential against Alzheimer's disease and other AD‐related neurodegenerative diseases, such as Prion disease." (PMID 35994714, 2022).
infectious disease (1 paper, 2020). A disorder directly resulting from the presence and activity of a microbial, viral, or parasitic agent in humans. "We speculate that the increased expression of RPSA in brain tissues following SS2 infection may be related to enhanced chemotaxis of PMNs to brain tissues, but the association between RPSA and PMNs in infectious diseases has not yet been reported." (PMID 33603733, 2020).
RPSA also shares sentences with these, for which no sentence is quoted: rheumatoid arthritis (3 papers); malignant melanoma (2); alcoholism (1); cholangiocarcinoma (1); corticobasal degeneration (1); degenerative arthritis (1); endometrial cancer (1); esophageal tumor (1); Flavivirus Infections (1); hematological malignancies (1); hepatocellular carcinoma (1); lentivirus infection (1); multidrug-resistant tuberculosis (1); oesophageal cancer (1); pneumonia (1); progressive supranuclear palsy (1); schwannoma (1); serous ovarian cancer (1); uveal melanoma (1).